IL6 (interleukin 6)
Diseases named in the same sentence as IL6 in open-access papers (continued):
Sharing a sentence is not in itself a finding about the gene and the disease.
Stroke (continued). "We tested the effects of MEDS-23 on levels of IL-6, PGE2 and TNF-α in the brains of post-stroke rats to elucidate whether it exerts anti-inflammatory effects that may explain its ability to alleviate the elevated BT (fever) observed in these animals." (PMID 35053779, 2021). "Moreover, we determined the effects of MEDS-23 on levels of the inflammatory mediators IL-6, TNF-α and PGE2 in various brain regions of post-stroke rats." (PMID 35053779, 2021). "Patients who died because of stroke during the follow-up time had higher levels of D-dimer, endostatin, IL-6, NT-proBNP, VAP-1, vWF, and TNF-R1 than patients who did not die." (PMID 33578805, 2021). "This is further supported by a more recent study which showed that fatigue may be associated with systemic inflammation, based on correlations with the serum levels of IL-6 and CRP, in community-dwelling stroke survivors up to 5 months post-stroke." (PMID 34884906, 2021). "Since NS19504 treatment promoted the outcome of stroke, we detected whether inflammation affects the significant difference between groups, and the mRNA levels of inflammation factors TNF-α, IL-1β, IL-6, IL-10, and TGF-β were examined." (PMID 34276309, 2021). "In addition, from the proposed biomarkers, we found that after adjusting for clinical variables, increased levels of endostatin, IL-6, and TNF-R1 were independent predictors of long-term mortality following stroke." (PMID 33578805, 2021). "It has been shown that IL-6 and TNF-α stimulate the synthesis and secretion of several chemotactic factors, which activate and attract peripheral blood leukocytes (neutrophils and monocytes) to the site of stroke lesions." (PMID 34433866, 2021). "The plasma level of IL-6, but not TNFα, sIL-6R, and IL-1ra, was higher in patients who developed depressive symptoms at 3 months after stroke (median: 4.7 vs 3.4 pg/mL, P = 0.06)." (PMID 33903586, 2021). "Third, IFN-γ is a potent inducer of other pro-inflammatory cytokines, such as IL-6, IL-1β and TNF-α, which may further the inflammatory response following the original stroke insult." (PMID 33919670, 2021). "In the Western blot assessment, the protein levels of TNF-α and IL-1β were increased, whereas no change was detected in IL-6 and IL-10 protein levels in the stroke mice at 3 days after stroke." (PMID 32010477, 2020). "IL-6 predicted OS, and IFN-γ predicted AMI events and stroke events." (PMID 33584644, 2020). "mRNA expression of pro-inflammatory cytokines, including IL-6, TNF-α, and CXCL1, were quickly increased after stroke and peaked at 24 h, whereas IL-1β, COX-2, and MCP-1 levels peaked at 48 h after stroke." (PMID 32867781, 2020). "Fourth, since plasma IL-6 levels, TNF release ex vivo, and GC resistance depend on stroke severity, one common biological mechanism induced by brain injury could be responsible for all these phenomena." (PMID 32107751, 2020). "IL-6, interleukin 1β (IL-1β) and tumor necrosis factor-alpha (TNF-α) are the major proinflammatory cytokines that provoke and aggravate an inflammatory response after stroke." (PMID 33192985, 2020). "IL-6 produces gliosis, activates endothelial cells, and increases BBB damage in stroke." (PMID 33362697, 2020). "One study investigated the predictive properties of biomarkers of immunodepression (mHLA-DR expression), as well as inflammation (IL-6), and infection (LBP) during the acute phase of stroke, and incidence of SAP stratified for patients with and without dysphagia." (PMID 31493069, 2020). "Cytokines, such as interleukin-1β (IL-1β), interleukin-6 (IL-6), interleukin-8 (IL-8), tumor necrosis factor-α (TNF-α), ficolin-1 and others, have been reported to increase in relations with the incident of stroke." (PMID 33036206, 2020).
Stroke (continued). "Intrahospital results revealed that IL‐6 level on day one PCS was significantly higher in patients who died prior to evaluation on day 5 PCS compared to survivors, indicating correlation between higher serum IL‐6 values and poorer prognosis in stroke patients." (PMID 32583980, 2020). "On the contrary, for all other cytokines measured (IL-1β, MCP-1, TNF-α, IL-1RA, and IL-6), secretions were reduced only from cocultures with healthy monocytes, and not from stroke-Mo at 24 hours." (PMID 32802081, 2020). "Treatments with LCN2 mAb within a clinically relevant time window significantly attenuated the induction of LCN2 mRNA and protein, pro-inflammatory mediators (iNOS, IL-6, CCL2, CCL9), infiltration of neutrophils, BBB leakage, and cerebral infarction, and improved functional outcomes after stroke." (PMID 32872405, 2020). "TNF-α and IL-6 are the main inflammatory factors involved in brain tissue damage; they are expressed at high levels in the early stage of ACI and are related to the infarct volume, neurological deficit, and prognosis after stroke." (PMID 33299456, 2020). "The results showed that MCAo increased the levels of pro-inflammatory cytokines while RIPC significantly decreased the levels of pro-inflammatory IL-1β, IL-6 and IFN-γ in the peripheral blood and that of IL-1β and IFN-γ in penumbra tissue 48 h post-stroke in aged rats." (PMID 32210788, 2020). "IL-6 IL-6 was co-expressed with glial fibrillary acidic protein (GFAP, astrocyte marker) but not with Iba-1 (microglia marker) or NeuN (neuron marker), indicating that the main cellular source of IL-6 is astrocyte during stroke recovery." (PMID 31133816, 2019). "Our findings reveal a previously unsuspected role for astrocytic IL-6-mediated negative immune regulation in the promoting effects of hyperforin on post-stroke neuroangiogenesis and long-term functional recovery." (PMID 31133816, 2019). "In stroke patients, neural tissue ischemia triggers an acute systemic inflammatory reaction characterized by a significant increase in blood C-reactive protein (CRP) and Interleukin-6 (IL-6)." (PMID 31614478, 2019). "Following a photochemically induced motor cortex stroke, treatment with DS2 at 0.1 mg/kg from 1 h post-stroke significantly decreased circulating tumor necrosis factor (TNF)-α, interleukin (IL)-17, and IL-6 levels, reduced infarct size and improved motor function in mice." (PMID 31736685, 2019). "The role of IL-6 in vascular inflammation and NIH pathology is supported by multiple in vivo and in vitro studies, with high levels of IL-6 in patients undergoing CABG correlating with graft occlusion and cardiovascular events such as stroke, myocardial infarction, and repeat CABG." (PMID 30719343, 2019). "Our results reveal a previously uncharacterized role of astrocytic IL-6-mediated negative immune regulation in the promoting effects of hyperforin on post-stroke neurovascular regeneration and functional recovery." (PMID 31133816, 2019). "Whole lung gene expression of IL-1β, TNF-α and MCP-1 was not altered at any of the time-points post stroke, but there was an increase in IL-6 and MIP-2α at the 6 h time-point." (PMID 30842652, 2019). "Previous reports characterized an acute immune response to ischemic stroke by profiling certain cytokines and chemokines (e.g., IL-1α and β, IL-6, IL-8, IL-9, IL-10, IL-12, IL-18, TNFα and soluble TNF-receptors p55, p75 and GRO-α) in the sera or cerebrospinal fluid of stroke patients." (PMID 31164999, 2019). "RIC alone without subsequent stroke obviously promoted plasma IL-6 expression without any impact on the concentration of IL-10 and TNF-α." (PMID 30115811, 2018). "Moreover, elevated levels of IL‐6 and TNF‐α have been also found in stroke patients with depressive symptoms (Su, Chou, Tsai, & Hung, 2012)." (PMID 29484258, 2018).
Stroke (continued). "In a study on endothelial cells conditionally lacking STAT3, the major transcription factor regulated by IL6, increased infarct volumes and reduced neo-vascularisation leads to impaired motor function in the mice after stroke." (PMID 29518129, 2018). "The pro‐inflammatory cytokines TNF‐α and IL‐6 are involved in the initiation or amplification of the inflammatory response, and higher levels of TNF‐α and IL‐6 have indicated the poor outcome of stroke." (PMID 29484258, 2018). "Additionally, we found that the concentrations of TNF-α, IL-6, IFN-r and IL-10 were significantly increased post-stroke." (PMID 30013463, 2018). "Interleukin 6 is important for protection against detrimental effects and for recovery in a stroke mouse-model and activated STAT3 regulates Vascular endothelial growth factor expression (VEGF), a growth factor important for angiogenesis after stroke." (PMID 29518129, 2018). "IL6 has previously been shown to be important for the vascularisation and recovery after stroke and treatment experiments have shown that IL6 can be used to reduce infarct volumes in a reperfusion mouse model (MCAO) of stroke." (PMID 29518129, 2018). "In contrast, exposure to BALF from Stroke or Sham animals did not change the phagocytic capability of alveolar macrophages, or the gene expression of IL-6 and TNF-α." (PMID 30290827, 2018). "Finally, several molecules involved in acute phase response signaling pathway, including IL-6 or TNF-α, have been consistently related to acute ischemic stroke and stroke recurrence." (PMID 29414888, 2018). "The regulation of IL-6 by PGZ may exert ambivalent beneficial effects in the early and late phase after stroke." (PMID 29110250, 2018). "We further demonstrated that IL-6 promoted angiogenesis in enriched animals after ischemic stroke, indicating that the promoting effects of astrocytic HMGB1 in the post-stroke angiogenesis and functional recovery were mediated by the secretion of IL-6 from astrocytes." (PMID 28845299, 2017). "A possible explanation for the lack of a decrease in IL-6 concentrations is that in comparison to the situation in stroke patients where it has an important prognostic role, CFS/ME patients exhibit no increase of this cytokine at baseline." (PMID 29284500, 2017). "Here, we found an increased plasma response in IL-6, CXCL1 and G-CSF in obese mice after stroke." (PMID 28798136, 2017). "In patients with stroke, HMGB1 levels are adequately associated with IL-6 levels but not with the magnitude of brain tissue damage as evaluated by CT morphometry." (PMID 29054968, 2017). "IL-6 expression was increased in all stroke mice regardless of housing conditions compared to their respective sham-operated group at 21 d.p.i." (PMID 28845299, 2017). "To confirm the inflammatory environment initiated by our stroke model, we measured increased proinflammatory cytokines IL-1β, IL-6, and Tnfα in the ipsilateral cortex, and this did not significantly change with 10 mg/kg decernotinib." (PMID 28790974, 2017). "When we performed a two-way ANOVA that was corrected for multiple comparisons, we found that G-CSF, IL-6, and KC/IL-8 were significantly different between C57BL/6 mice and humans, and G-CSF and IL-6 were significantly different between BALB/c mice and humans at this acute stage of stroke." (PMID 27600707, 2016). "However, after sex stratification we found that IL1A, IL1B, IL6, IL8, TNF and other 13 anti-stroke targets were all up-regulated in male patients." (PMID 27672514, 2016). "SAI patients had significantly higher IL-6 and IL-10 levels and lower HLA-DR levels than no-infection patients within 48h after stroke onset." (PMID 27409177, 2016). "In addition, IL1A, IL6, TNF and other anti-stroke targets were also presented an up-regulated trend." (PMID 27672514, 2016).
Stroke (continued). "SAI patients had significantly higher IL-6 (Std.MD 2.35; 95%CI 0.82–3.89; P=0.003) and IL-10 (Std.MD 1.08; 95%CI 0.09–2.06; P=0.03) levels compared to stroke patients without infection within 48h after stroke onset." (PMID 27409177, 2016). "Despite the presence of IL-17A-positive lymphocytes in autoptic brain of stroke patients, IL-17 blood level does not seem to be a good predictor of stroke outcome as compared to other cytokines such as IL-6." (PMID 25972779, 2015). "We have noted that Npas4−/− mice had both increased IL-6 and TNF-α expression post-stroke." (PMID 26690124, 2015). "We hypothesized that early levels of the inflammatory and anti-inflammatory markers LBP, IL-10, IL-6 and CRP are biomarker candidates for the prediction of post-stroke infections in acute ischemic stroke patients." (PMID 25613713, 2015). "Stroke subjects also showed higher cytokine plasma levels such as TNF-α (28.2 ± 29.3 vs 12.3 ± 4.5 pg/mL; P = 0.0001), IL-1β (7.9 ± 2.6 vs 4.7 ± 1.6 pg/mL; P = 0.0001) and IL-6 (8.2 ± 2.4 vs 4.2 ± 1.5 pg/mL; P = 0.0001) compared to controls." (PMID 25997053, 2015). "We focused on such factors, i.e. IL-6, CD68, CCL3 and CCL5, which have already been described by us and others occurring in the ischemic peri-infarct area and being relevant for tMCAO-induced brain damage and post-stroke therapy." (PMID 24024100, 2013). "IL-6, CRP, age, NIHSS score and dysphagia may be predictive factors for the occurrence of pneumonia on the day of stroke symptom onset." (PMID 23935729, 2013). "Interestingly, large stroke and ICH resulted in a prolonged increase of IL-6 and IL-1β concentration until follow-up, resulting in a still 2-fold increase of IL-1β compared to controls." (PMID 24069356, 2013). "Inflammatory cytokines, such as IL-1β, IL-6, and TNF-α, are secreted by activated microglial cells and macrophages in stroke lesions and induce the expression of chemokines, which recruit more circulating monocytes/macrophages into lesions and lead to further brain damage." (PMID 23431245, 2013). "IL-6, CRP, age, NIHSS score and dysphagia may predict the occurrence of pneumonia on the day of stroke symptom onset." (PMID 23935729, 2013). "SDMA and ADMA are not correlated with IL-6 during the first 24 hours after stroke onset but we observed a correlation days after the event." (PMID 23158556, 2012). "Overexpression of UCP2 significantly reduced the IL-6 expression to less than one third of the levels observed in wild-type animals after being challenged with ischemia, suggesting that UCP2 suppresses neuroinflammation in the brain after stroke." (PMID 22348126, 2012). "There was a negative correlation between the initial IL-6 levels and functional outcome (BI) of stroke at 1 month (r = - 0.45: P < 0.05)." (PMID 21450100, 2011). "MBL-low patients showed a cytokine profile after stroke characterized by a greater increase of IL-10, a lower rise of IL-6, and no significant changes of TNF-α compared to patients with MBL-sufficient genotypes." (PMID 20140243, 2010). "The results show that IL-6, CRP, and to a lesser extent, fibrinogen are more closely linked to risk of fatal MI or stroke (i.e., fatal CVD) than to nonfatal vascular events in the elderly at risk." (PMID 19554082, 2009). "Among stroke patients, IL-6 and IL-1 receptor antagonist, but not TNFα, measured at baseline were independent predictors of worsening in the first 24 hours after stroke." (PMID 17042946, 2006). "The evidence indicates distinct prognostic patterns: biomarkers of inflammation (e.g., TNF-α, IL-6, IL-1β) and neuronal or glial damage (e.g., S100B, GFAP, NSE, NfL) tend to correlate with less favorable outcomes, especially when measured in the acute phase of a stroke." (PMID 41598337, 2026).
Stroke (continued). "Additionally, cystatin C activates inflammatory pathways (e.g., NF-κB) and promotes the release of pro-inflammatory cytokines (e.g., IL-6, CRP), establishing a vicious cycle of post-stroke neuroinflammation and delayed neuronal death, significantly increasing all-cause mortality." (PMID 40941489, 2025). "Studies have revealed that the NF‐κB signaling pathway is over‐activated in microglial cells following a stroke, serving as a crucial regulator of the inflammatory response by driving the transcription of downstream pro‐inflammatory cytokines such as IL‐1β, TNF‐α, and IL‐6." (PMID 40237440, 2025). "Furthermore, we found that RA and other invasive procedures had similar risks for short-term MACEs, mortality, TVR, slow/no flow, stent thrombosis, in-stent restenosis, heart failure, stroke, emergency CABG, contrast volume, and inflammation (i.e., Interleukin-6)." (PMID 40807011, 2025). "However, the relationship between IL-6 and cognitive decline after a stroke is not fully established." (PMID 40305179, 2025). "By delving into the molecular underpinnings of IL-6 and TNF-alpha involvement in ischemic stroke, we hope to uncover novel insights that could pave the way for more effective and targeted interventions in stroke management." (PMID 39859987, 2025). "IL-10 levels can rise within the first few hours after stroke, although the increase may not be as immediate as other pro-inflammatory cytokines like IL-6 or TNF-α." (PMID 40142325, 2025). "Therefore, the detection and targeted intervention of concentrations of IL-1β, IL-6 and TNF-α post-stroke may contribute to the diagnosis and treatment of PSD." (PMID 38377025, 2024). "Therefore, it is crucial to include objective and readily available predictors for better predictive model performance, such as inflammatory biomarkers interleukin-6 (IL-6) or C-reactive protein (CRP), which have been shown to be related to an increase in OSA in stroke patients in previous studies." (PMID 38268059, 2024). "An important phenomenon after stroke is the systemic immunosuppressive effect, which usually manifests as splenic atrophy accompanied by increased apoptosis or cellular dysfunction, along with the suppression of numerous inflammatory factors, including IL10, IL-1b, TNF-α, and IL-6." (PMID 38637850, 2024). "Yang and coworkers also reinforced the role of IL-6 and other cytokines like IL-1β and TNFα in disruption of blood–brain barrier (BBB), leading to neurological degeneration in such diseases as Alzheimer’s disease (AD), stroke, multiple sclerosis (MS), and posttraumatic brain injury (TBI)." (PMID 38093175, 2023). "Thus, MLC601 and MLC901 reduce infarct size and ischemia-induced neurological deficits, attenuate cerebral ischemia-induced pro-inflammatory cellular infiltration, and attenuate stroke-induced increased expression of pro -inflammatory mediators (IL11, IL1β, IL6 and TNFα) in the brain." (PMID 36975881, 2023). "In addition, post-stroke death at 6–12 months was predicted by increased LOOH levels in conjunction with lowered antioxidant levels (25(OH)D), metabolic (FBG) and inflammatory (IL-6) biomarkers." (PMID 36671047, 2023). "In addition, butyric acid could inhibit the activation of the microglia and astrocytes in the brains of model mice, thereby inhibiting the generation of pro-inflammatory factors IL-6, IL-1β and TNF-α as well as improving stroke outcomes." (PMID 38201839, 2023). "IL‐6 expression levels are increased following IS and HS28, 29; however, there are conflicting reports of whether blocking IL‐6 signaling is beneficial or detrimental following stroke." (PMID 36478506, 2023). "Finally, some potential indicators, such as the size of the stroke area, and other biomarkers of inflammation(i.e.,IL-6, TNF-α) were not included in the study." (PMID 36206280, 2022). "Furthermore, IL-6 gene expression was increased in macrophages and endothelial cells but not in epithelial cells isolated from stroke animals’ lungs." (PMID 36119128, 2022).